POLQ (DNA polymerase theta)
Diseases named in the same sentence as POLQ in open-access papers (continued):
Sharing a sentence is not in itself a finding about the gene and the disease.
cancer (continued). "Recent studies have demonstrated that inhibition of PolQ in DSB repair-deficient cancers, as in the case of PARP-1, also results in synthetic lethality." (PMID 34490123, 2021). "DNA polymerase theta, encoded by the human POLQ gene, is upregulated in several cancers and is associated with poor clinical outcomes." (PMID 34206946, 2021). "Following the same line, the present study highlights the importance of POLQ as a prognostic factor associated with worse survival in different types of cancer (especially Group A and D)." (PMID 34853396, 2021). "We define here the POLQ-associated mutation signatures in human cancers, characterized by short insertions and deletions in a specific range of microhomologies." (PMID 32885167, 2020). "Prior studies have also observed an association between POLQ overexpression in cancer with BRCA1/BRCA2 mutation and an over-representation of TMEJ-associated genomic scars." (PMID 33385162, 2020). "In this study, we have demonstrated that specific COSMIC signatures, SBS3 and ID6 and ID8, are enriched in BRCA-mutated cancers that express high levels of wild-type POLQ." (PMID 32885167, 2020). "Other mutational signatures including SBS40, SBS5, ID9, ID1 and ID2 were not significantly enriched more in BRCA1/2-mutated cancers expressing wild-type POLQ than in other types of cancers." (PMID 32885167, 2020). "SBS3, ID6 and ID8 signatures were significantly enriched more than other types of mutation signatures in BRCA1/2-mutated cancers expressing wild-type POLQ." (PMID 32885167, 2020). "SBS3, ID6 and ID8 were enriched more in BRCA1/2-mutated cancers expressing high levels of wild-type POLQ than in other conditions." (PMID 32885167, 2020). "The requirement of POLQ for the viability of BRCA-mutated cancer cells underscores the importance of TMEJ." (PMID 32885167, 2020). "E + Q and E + Z mutant tumors also displayed significantly higher mutation counts compared to E-only mutant tumors, suggesting a contribution of mutationally altered POLQ or POLZ/REV3L to the overall cancer mutation rates." (PMID 32838755, 2020). "Here, we describe experiments to analyze which COSMIC signatures are enriched among 82 signatures in BRCA-mutated cancers that express high levels of wild-type POLQ." (PMID 32885167, 2020). "Other mutational signatures including SBS40, SBS5, ID9, ID1 and ID2 were also enriched in BRCA1/2-mutated cancers expressing high levels of wild-type POLQ." (PMID 32885167, 2020). "Consistent with this notion, association of the POLQ expression level with the number of non-synonymous mutations has also been reported in carcinomas of the breast, ovary, and uterus." (PMID 31137743, 2019). "It is likely that POLQ is a unique TLS polymerase gene from the standpoint of the somatic mutation burden in carcinomas." (PMID 31137743, 2019). "Depleting of POLQ in human cancer cells caused an increase in IR-induced γH2AX foci and sensitized the cells to γ-irradiation." (PMID 27533083, 2016). "Overexpression of POLQ, the gene encoding Polθ, is a prognostic marker for an adverse outcome in a wide range of human cancers." (PMID 27612511, 2016). "In addition to its previously reported requirement for survival in BRCA1/2 mutated cells, POLQ would protect cancer cells with functional canonical DSBs repair mechanism from the accumulation of DNA replication associated DSBs." (PMID 39435280, 2024). "Additionally, POLQ inhibition in this type of cancer with BRCA2 deficiency is synthetically lethal as expected, but also stimulates the immune response." (PMID 39435280, 2024). "MSH6 and POLQ may have slightly different potential cancer-associated trends in women and men, respectively." (PMID 36896836, 2023).
cancer (continued). "In this study, we address these compelling scientific and experimental challenges using our bespoke telomere fusion sequencing capacity in association with whole genome sequencing (WGS) in two independent wild-type (WT) and POLQ-deficient human cancer cell lines transiting telomere-driven crisis." (PMID 35774233, 2022). "Targeting mediators of microhomology-mediated end joining (MMEJ) POLQ and PARP1 also had a statistically significant viability reducing and DNA damage increasing effect on the cells supporting the concept of synthetic lethality of POLQ (polymerase theta, Polθ) inhibition in HR deficient cancers." (PMID 34084283, 2021). "POLQ overexpression has also been observed in cancers with BRCA1/BRCA2 mutation, suggesting that it may represent an adaptive response to elevated replication-associated DSB burden, although the precise mechanism of upregulation remains to be elucidated." (PMID 33385162, 2020). "However, they were not significantly enriched more in BRCA1/2-mutated cancers expressing wild-type POLQ than in other types of cancers." (PMID 32885167, 2020). "Since somatic mutations in cancer-associated genes can lead to an exacerbation of the malignant potential, POLQ overexpression could be a key event in the pathogenesis of LAC." (PMID 31137743, 2019). "While increased Polθ dosage was recently suggested to promote survival of homologous recombination (HR)-deficient cancer cells, it remains unclear whether POLQ overexpression could be also beneficial to HR-proficient cancer cells." (PMID 27612511, 2016). "Moreover, there are multiple reports that POLQ is upregulated in cancer cells, also those with HR-deficiency, which could correlate with higher sensitivity to Polθ inhibition." (PMID 39273083, 2024). "Interestingly, the Polθ function, which plays an important role in determining the RT of early-replicating domains, seems to be particularly important within the cancer context, as high POLQ expression is strongly associated with poor clinical outcomes in several cancers." (PMID 33946274, 2021). "POLQ may process those DSBs especially in BRCA-mutated cancers." (PMID 32885167, 2020). "We therefore explore in this work whether we could find genetic vulnerabilities associated with POLQ overexpression of HR-proficient cancer cells and if upregulation of Polθ could be selected during tumorigenesis in order to adapt to high levels of endogenous or external replicative stress." (PMID 27612511, 2016). "In order to explore whether and how POLQ overexpression could be beneficial in HR-proficient cancer cells, we first investigated if we could find genetic vulnerabilities associated with POLQ overexpression of HR-proficient cancer cells under normal growth conditions." (PMID 27612511, 2016). "We obtained the expression level of POLQ from a pan-cancer perspective through the TCGA database, which showed a statistical overexpression of POLQ in 21 types of malignancies." (PMID 39520627, 2024). "Consistently as anticipated, the pan-cancer analysis from the TCGA public database revealed that POLQ was highly expressed in nearly all tumor types due to increased replication stress and frequent DNA damage within tumors." (PMID 38270643, 2024). "Although POLQ participates in maintaining genome stability, several studies have shown that its overexpression correlates with cancer progression and poor prognosis." (PMID 39435280, 2024). "At present, more research has begun to focus on the A-EJ pathway (especially its component DNA polymerase-θ, POLQ) as a potential therapeutic target for cancer cells with impaired NHEJ or HR activity." (PMID 39334297, 2024).
cancer (continued). "POLQ is a promising target in cancer therapy, and POLQ inhibitors are being actively developed by the scientific and industrial communities." (PMID 38370403, 2024). "DNA polymerase theta (Pol theta, encoded by the POLQ gene) is critical for microhomology annealing and fill-in synthesis, and is essential in HR-defective cancers and in cells with other DSBR defects." (PMID 38906885, 2024). "Previous research indicates that POLQ helps to maintain genome stability while its expression correlates with cancer progression and poor prognosis." (PMID 39435280, 2024). "Positive RNA–RNA correlations were widespread between POLQ and multiple cancer driver genes most notably BRCA2." (PMID 39166898, 2024). "Studies have shown that POLQ is upregulated in HR-deficient cancers, including those with BRCA1/2 PVs, and inhibiting POLQ leads to micronuclei formation and IFN signaling." (PMID 39682099, 2024). "In contrast, other DNA damage response and repair genes, including BRCA1, BRCA2, ATM, BRIP, POLQ, and CDK12, were significantly more often mutated in CDX2-suppressed cancers." (PMID 39452477, 2024). "In this study, TCGA pan-cancer analysis revealed elevated expression of POLQ in various cancers, including ccRCC, and its expression levels were correlated with tumor stage." (PMID 38270643, 2024). "In a previous study, it has been noted that POLQ is overexpressed in BC, which leads to a poor prognosis, and this overexpression also has effects on key cancer pathways." (PMID 39272813, 2024). "Although POLQ is undetectable in most normal tissues, it is frequently overexpressed in many cancers and correlates with a poorer prognosis." (PMID 36976649, 2023). "The most frequent genes in patients with cancer were DNA polymerase theta (POLQ; n = 6) and MSH6 (n = 4) in women and POLQ (n = 4) in men." (PMID 36896836, 2023). "In terms of cancer-related genes, POLQ and PREX2 in the regions of gains and CASP8 and SF3B1 in the regions of loss were found in all samples, including the tissue, plasma, and peritoneal fluid." (PMID 35626111, 2022). "Studies showed that POLQ‐addicted cells and cancers had a similar GIN feature, showing an increased prevalence of alt‐NHEJ‐related microhomology‐flanked deletions." (PMID 35726713, 2022). "Recent studies show that PARPi-tolerant cancer cells have relatively higher POLQ expression, and they are sensitive to POLQ inhibitor." (PMID 35281059, 2022). "Accordingly, analysis of CFSs in cancer genomes reveals frequent allelic deletions, flanked by signatures of POLQ-mediated repair." (PMID 36344511, 2022). "The expression of POLQ is normally repressed in somatic cells but upregulated in several human cancers." (PMID 34206946, 2021). "Recently, it has been proposed that the overexpressed POLQ neutralizes the excessive genome instability in cancer cells, which frequently possess higher levels of replication stress." (PMID 34206946, 2021). "DNA polymerase theta (Polθ) is a validated anti-cancer drug target that is synthetic lethal with HR factors and other DNA repair proteins and confers cellular resistance to various genotoxic cancer therapies." (PMID 34440316, 2021). "In the past decades, accumulating evidence showed that POLQ also participate in the development and progression of human cancers because of its critical functions in the repair of genomic double-strand breaks." (PMID 34517891, 2021). "Remarkably, the present work also demonstrated that higher expression of UBE2T, RFC4, POLQ, BRIP1, and H2AFX is especially associated with worse overall survival (HR > 5) in several types of cancer (Group A and D)." (PMID 34853396, 2021).
cancer (continued). "Cancer cells with compromised homologous recombination, or other DNA repair defects, over-utilize end-joining by polymerase θ and often over-express the POLQ gene." (PMID 34573292, 2021). "Cancers with mutations in POLE and POLQ (E/Q), POLE and POLZ/REV3L (E/Z) and in all 3 polymerases (E/Q/Z) were associated with the highest mutation burden and an excellent prognosis independent of MSI status and tumor stage." (PMID 32838755, 2020). "It is crucial to identify tumors that rely on POLQ activity for DSB repair, because such tumors are defective in other DSB repair pathways and have predicted sensitivity to POLQ inhibition and to cancer therapies that produce DSBs." (PMID 32885167, 2020). "This unique activity of POLQ yields a distinctive mutation pattern that has been proposed to be related to COSMIC3, a mutational signature often found in BRCA-mutated cancers." (PMID 32885167, 2020). "These cancers also had high rates of ATM, POLQ, FANCM mutations, as well as those to several other genes." (PMID 33214570, 2020). "The variants in cancer driver genes, MSH6, POLQ, ARID5B, and IDH2, warrant further study to determine the mechanism by which these variant affect cancer progression." (PMID 32066500, 2020). "Prognostic variants were identified in or near MSH6, POLQ, ARID5B, and IDH2, which are previously reported cancer driver genes." (PMID 32066500, 2020). "Using human cancer cells with disruptions of POLQ, we further show that TMEJ dominates end joining of two separated DSBs (distal EJ)." (PMID 32885167, 2020). "An analysis on human breast cancers found that of the 14 nuclear DNA polymerase genes, only POLQ expression was significantly higher in the cancer tissues in comparison to normal tissues." (PMID 29301327, 2018). "Further studies are warranted to define the functional impact of mono and bi-allelic alterations of POLQ on HR DNA repair in human cancers." (PMID 29021619, 2017). "Further, recent studies have suggested that cancer cells with defective HR are dependent on POLQ-mediated MMEJ repair." (PMID 27131361, 2016). "The recent discovery that HR-deficient tumours are dependent on repair by POLQ also argues that HR and alt-EJ can act on similar substrates, and importantly identifies POLQ as a druggable candidate target for cancer therapy." (PMID 26077599, 2015). "Moreover, POLQ is found exclusively in cancer cells, suggesting that it acts as a compensatory mechanism that ensures cancer cell survival." (PMID 40149342, 2025). "The discovery that POLQ is a key prognostic biomarker in AML may have a therapeutic value because cancer cells, including AML cells overexpressing Polθ protein are hypersensitive to Polθ inhibitors which are currently in clinical trials against solid tumors." (PMID 38734788, 2024). "POLQ is an error-prone polymerase and is upregulated in numerous cancers." (PMID 38685010, 2024). "Cancer cells usually show increased expression of POLQ, which would favor their survival." (PMID 39435280, 2024). "To explore whether POLQ mediated the effects of iron on regulating cancer cell platinum sensitivity, we employed siRNA to silence POLQ expression." (PMID 38740757, 2024). "Therefore, the differences in expression between cancer and normal tissues, and its role in survival and evolution of cancer cells have made POLQ a potential therapeutic target in cancer treatment." (PMID 39435280, 2024). "Notably, cancer cells harbouring BRCA1/2 PVs commonly rely on alternative repair pathways such as polymerase θ (POLQ)-mediated alternative end-joining and radiation sensitive 52 (RAD52)-mediated single-strand annealing." (PMID 39682099, 2024).
cancer (continued). "The development of protocols to analyze POLQ expression by IHC could be helpful in other cancers, since the increase in POLQ abundance takes place in most of the tumors analyzed and in the different tumor data included in GEPIA." (PMID 39435280, 2024). "Currently, there are few reports regarding the role of POLQ in cancer." (PMID 39046429, 2024). "To investigate the capacity of POLQ-deficient cells to escape a telomere-driven crisis, we employed retroviral transduction to suppress telomerase function in two independent human cancer cell lines, HCT116 and HAP1, that had undergone CRISPR/Cas9-mediated mutation of the POLQ gene." (PMID 35774233, 2022). "Conversely, overexpression of POLQ may confer resistance to replication stress, contributing to poor patient prognosis in cancer." (PMID 35774233, 2022). "POLQ over‐expression was related to poor prognosis in many cancers." (PMID 35726713, 2022). "Nonetheless, our results indicate that NVB may have additional POLQ-independent effects that will need to be considered for inclusion of this antibiotic in cancer treatment regimes." (PMID 35774233, 2022). "Our findings uncover novel considerations for the efficacy of POLQ inhibitors in clinical cancer interventions, where potential genome destabilizing consequences could drive clonal evolution and resistant disease." (PMID 35774233, 2022). "POLQ expression in different cancer types strongly correlated with the expression of factors involved in response to replicative stress (RAD51, FANCD2, and BLM), instead of genes encoding for several core MMEJ proteins, factors involved in DNA end resection or in canonical NHEJ." (PMID 34201502, 2021). "Notably, recent examination of genomic data and results from TCGA analysis have demonstrated that not only do HPV+-tumors show marked dependency on MMEJ to repair DSBs, but also that POLQ is up-regulated compared to HPV- cancers." (PMID 34490123, 2021). "DNA polymerase theta (Pol θ) is a predominant mediator of the MMEJ pathway (named TMEJ), that generates short insertions and deletions, associated with specific mutational signatures in human cancers." (PMID 34201502, 2021). "In addition, we would like to point out that the association of overexpression with an increased number of somatic mutations was observed at a low frequency for the 9 TLS polymerases examined, other than POLQ, in the 18 cancer types included in the analysis." (PMID 31137743, 2019). "Furthermore, a study of colorectal cancer patients found that cancer patients with higher expression of a group of 47 DNA-replication-related genes which includes POLQ in tumors correlated with poorer patient survival." (PMID 29301327, 2018). "Interestingly, in two of these cases variants of genes involved in genome (POLQ) or chromatin (SETD4) stability were detected, so these findings also open new avenues for investigating cancer susceptibility." (PMID 28050010, 2017). "We also analysed whether POLQ deregulation in cancer could be part of a global deregulation of genes involved in the response of replicative stress in vivo by datamining gene expression data from published cancer studies." (PMID 27612511, 2016). "It has been suggested that suppression of POLQ may be useful in increasing the efficacy of DNA damaging treatments in cancer." (PMID 25275444, 2014). "Unexpectedly, the Burkitt lymphoma translocation (a major cancer-associated genome instability) is enhanced in the absence of POLQ." (PMID 25275444, 2014). "In view of the in vitro evidence linking POLQ expression to tumour cell radioresistance, we hypothesised that POLQ overexpression may increase the likelihood of treatment failure in cancer patients, and therefore confer an adverse clinical prognosis." (PMID 20700469, 2010).